BCL2 (BCL2 apoptosis regulator)
Diseases named in the same sentence as BCL2 in open-access papers (continued):
Sharing a sentence is not in itself a finding about the gene and the disease.
lupus (continued). "B-cell lymphoma 2 (Bcl-2) is critical for pDC survival and IFN-I production in lupus mice or patients with SLE, and the use of the selective Bcl-2 inhibitor venetoclax (ABT-199) significantly reduces auto-reactive B cell and total lymphocyte counts and alleviates disease symptoms in female patients." (PMID 37183207, 2023). "Interestingly, the anti-apoptotic molecule Bcl-2 was also downregulated upon curcumin treatment, which is consistent with the speculation that curcumin may abrogate immune responses via promoting apoptosis of immune cells in the peripheral lymphoid tissue such as the spleen in lupus." (PMID 32143311, 2020). "Numerous other agents such as Bcl-2 antagonists, Btk inhibitors and dihydroartemisinin have shown promise in reducing levels of circulating Type I IFN in laboratory and animal models of lupus." (PMID 32185249, 2017). "pDCs in lupus are constantly stimulated by TLR7/9 ligands, which are known to suppress miR-29b and miR-29c, allowing for upregulation of the target of these microRNAs, including Bcl-2." (PMID 27034965, 2016). "In individuals with systemic lupus erythematosus (SLE) and Sjogren’s syndrome, increased TRIM21 expression downregulates BCL2, promotes extensive apoptosis, and compromises intracellular immunity." (PMID 38225560, 2024).
adenoma (28 papers, 1996 to 2023). A neoplasm arising from the epithelium. "The positive association with BAX led to an inverse association for the BCL2/BAX ratio with increasing adenoma size (p-trend<0.0001)." (PMID 34762658, 2021). "Bcl-2 is upregulated in adenomas, and its loss or inhibition impairs outgrowth of oncogenic clones, because Bcl-2 alleviates apoptotic priming in epithelial cells following Apc loss." (PMID 26956214, 2016). "Strikingly, our data revealed an increased formation of cyst-like structures on combined Apc and Bcl-2 loss within the Lgr5+ ISCs at the expense of adenoma formation." (PMID 26956214, 2016). "Similarly, single-cell karyotype sequencing to quantify copy number alterations revealed no 18q LOH in any of the TA cultures, thereby excluding LOH as the underlying mechanism of decreased BCL-2 expression in adenomas." (PMID 34117376, 2021). "Furthermore, even heterozygous loss of Bcl-2 resulted in a threefold reduction in the number of adenomas." (PMID 26956214, 2016). "Increased BCL2 in FZD9-/- adenomas suggested an effect of FZD9 loss on cell survival, so we measured apoptosis proteins in the WT and FZD9-/- adenoma cell lines by protein dot blot." (PMID 35924166, 2022). "It was found that Bcl‐XL instead of Bcl‐2 or Mcl‐1 is required for cell survival and outgrowth during the adenoma‐to‐carcinoma sequence of CRC." (PMID 36254394, 2022). "Other studies have observed lower BCL2 expression in villous compared to tubular adenomas, as well as in carcinomas compared to adenomas." (PMID 34762658, 2021). "Score 1 and score 2 Bcl-2 staining was detected in 38.4% (n = 78/203) and 57.6% (n = 117/203) of adenomas, respectively." (PMID 33579312, 2021). "Cyclin D1 LI, p16 LI and p21 LI were lower in adenomas compared to serrated lesions, while expression of both BCL2 and BAX were higher (p <0.001)." (PMID 34762658, 2021). "We examined the most commonly upregulated microRNAs in early adenomas and found several of them to have binding sites on the BCL-2 3′UTR, as predicted by miRmap." (PMID 34117376, 2021). "ISC-specific knockdown of BCL-2 severely impaired adenoma outgrowth in mice, as did treatment with the specific inhibitor ABT-199." (PMID 34117376, 2021). "While intestinal stem cells (ISCs) require BCL-2 for adenoma outgrowth and survival during transformation, ISC-specific MCL1 deletion results in disturbed intestinal homeostasis, eventually contributing to tumorigenesis." (PMID 34117376, 2021). "Altogether these results indicate that BCL-2 exerts its pro-survival functions during transformation alone while BCL-XL is required for apoptosis evasion throughout the adenoma-to-carcinoma sequence." (PMID 34117376, 2021). "This revealed a significant decrease in BCL-2 expression in adenomas compared to healthy tissue and a further decrease in CRC tumors, which was also confirmed in the TCGA COREAD cohort." (PMID 34117376, 2021). "BCL-2 is expressed in crypt stem cells and plays a critical role in facilitating intestinal stem cell transformation and adenoma survival." (PMID 32335811, 2020). "In stem cell-specific BCL-2 null mice, loss of APC gives rise to significantly fewer adenomas, thus indicating that BCL-2 is crucial for tumor initiation and survival." (PMID 32335811, 2020). "While BCL-2 plays a key role in adenoma formation, a progressive decrease in its expression during tumor progression indicates less of a role in CRC survival and resistance." (PMID 32335811, 2020). "One study has reported increased proportion of Bcl-2 expression in adenomas than in carcinomas, indicating the role of Bcl-2 in early neoplastic transformation." (PMID 31754362, 2019). "Genetic as well as pharmacological inactivation of BCL-2 impairs adenoma formation and results in formation of indolent lesions similar to cyst-like structures observed when oncogenic mutations are introduced in the differentiated cell pool." (PMID 26956214, 2016).
adenoma (continued). "A tissue microarray (TMA), containing adenoma, adenocarcinoma and normal mucosa specimens was stained for Bcl-xL, Mcl-1 and Bcl-2." (PMID 27537525, 2016). "We observed that 30 days after tamoxifen administration, simultaneous inactivation of Apc and Bcl-2 resulted in significantly impaired adenoma formation." (PMID 26956214, 2016). "To determine the importance of Bcl-2 in established adenomas we evaluated Bcl-2 expression in adenomatous tissue." (PMID 26956214, 2016). "We observed that, similar to normal crypts, BCL-2 expression matches Lgr5-GFP expression suggesting a specific role of Bcl-2 in stem-like cells in adenomas." (PMID 26956214, 2016). "Compared with nonneoplastic mucosa, there was significantly increased staining for bcl-2, caspase-3, and cyclin-D1 in all adenomas combined (χ2 > 25, P < 0.01)." (PMID 23476634, 2013). "There was a statistically significant decrease in staining frequency in carcinomas compared with adenomas for bcl-2 (χ2 = 6.23, P = 0.012)." (PMID 23476634, 2013). "While the apoptotic effector protease caspase-3 is upregulated in adenomas and persists in carcinomas, the antiapoptotic regulator bcl-2 is upregulated in adenomas, but downregulated in invasive carcinomas." (PMID 23476634, 2013). "In sporadic tumours, several studies have shown consistent results, with bcl-2 expressed in 80%–90% of adenomas, but the expression was reduced to 30%–50% in carcinomas." (PMID 23476634, 2013). "We find that beta-catenin and related proliferative and apoptotic factors (cyclin-D1, bcl-2, caspase-3, and Ki-67) are expressed early in the sequence, in adenomas." (PMID 23476634, 2013). "Bcl-2 staining was cytoplasmic and nuclear and seen in 68 low grade adenomas (48.6%) and 6 high grade adenomas (50%)." (PMID 23476634, 2013). "bcl-2 expression was observed in 14 of 36 cases (39%) with adenoma, five of 33 (15%) with LPM (P< 0.05) and 12 of 63 (19%) with carcinoma (P< 0.05)." (PMID 10780525, 2000). "In addition, whereas normal colonic epithelial cells are dependent on BCL2, there is a shift in the intestinal adenoma phase to BCL-xL, thus, BCL-xL inhibitors are suggested to have a more profound effect in CRC." (PMID 37511344, 2023). "BCL2 is elevated in FZD9-/- adenomas, suggesting increased avoidance of apoptosis." (PMID 35924166, 2022). "Also, in concordance with previous studies, we observed lower BCL2 expression in serrated lesions than in adenomas." (PMID 34762658, 2021). "Bcl-2 overexpression might substantially contribute to the development of FAP adenomas by means of its antiapoptotic potential." (PMID 33579312, 2021). "Treatment with ABT-199 while intestinal stem cells are undergoing APC deletion and hence transformation strongly impairs adenoma outgrowth, which suggests that BCL-2 is a potential target for CRC chemoprevention in patients with high risk conditions such as familial adenomatous polyposis." (PMID 32335811, 2020). "A similar pattern of BCL-2 distribution was seen in human adenomas." (PMID 26956214, 2016). "This suggests that these structures do not reflect a gained property of Bcl-2 deficient cells, rather they are more visible given the lack of efficient adenoma formation." (PMID 26956214, 2016). "Based on these reports, we suggest that anti-apoptotic gene Bcl-2 which have differential gene expression between LSTs-adenoma and Ip-adenoma may play an important role in the morphogenesis of LSTs by being responsible for apoptotic expression." (PMID 26048755, 2015). "Bcl-2 expression was increased in adenomas, but decreased in carcinomas." (PMID 23476634, 2013).
adenoma (continued). "Our study shows 48.7% of adenomas being positive for bcl-2 but only 5.6% positivity in carcinomas." (PMID 23476634, 2013). "However, Bcl-2 immunoreactivity has been demonstrated not only in adrenal cortical lesions (cortical hyperplasia, adenomas and carcinomas) but also in normal cortical tissue." (PMID 12085205, 2002). "A higher proportion of adenomas (63.2%) than carcinomas (36.5%) expressed bcl-2 (P < 0.05)." (PMID 8611422, 1996). "We also tested whether ARC correlated with Bcl-2 expression in FAP adenomas." (PMID 33579312, 2021). "We speculated that BCL-2 inhibition might promote cell death in established adenomas." (PMID 26956214, 2016). "From 13 cases containing tumour-associated adenoma, four were Bcl-2 negative in premalignant and malignant cells, in another four cases these cells showed similar staining intensities and in the remaining cases only the malignant colorectal cells were Bcl-2 negative." (PMID 9667656, 1998). "It is also possible that other Bcl-2 family members such as Bcl-XL or Bcl-W are upregulated in the adenomas, rendering ABT263 less effective, given that Bcl-2 is the critical ABT-263 target in vivo." (PMID 36860494, 2022). "Adenomas also displayed higher pro-apoptotic BAX and anti-apoptotic BCL2 expression compared to serrated lesions." (PMID 34762658, 2021). "In our study, Bcl-2 was weakly overexpressed in 38.4% and strongly overexpressed in 57.6% of the FAP adenomas evaluated." (PMID 33579312, 2021). "A significant correlation was found between Bcl-2 staining and both cytoplasmic (p = 0.001) and nuclear (p = 0.045) ARC staining in FAP adenomas." (PMID 33579312, 2021). "Although there were scant adenomas left for analysis from the combination treatment, the reduction of COX2, MYC, and BCL2 in the mebendazole only tumors also points to reduced inflammation beyond sulindac alone." (PMID 27612418, 2016). "Regitnig and Denk determined that apoptotic fragments of epithelial cells remained in the epithelium of adenomas, accompanied by a reduction in macrophage levels and an increased expression of Ki-67 and Bcl-2 in adenoma tissue without melanosis." (PMID 37214441, 2023). "Previously, we have shown BCL-2 inhibition with ABT-199 to effectively reduce adenoma burden in vivo while in our study this effect is no longer apparent." (PMID 34117376, 2021). "Like Bcl-2, increased COX-2 expression has been observed in FAP adenomas before." (PMID 33579312, 2021). "By targeting antiapoptotic proteins with specific BH3 mimetics in organoid models of CRC progression, we found that BCL-2 is essential only during ISC transformation while MCL1 inhibition did not affect adenoma outgrowth." (PMID 34117376, 2021). "While several studies find an increase in BCL-2 protein levels in adenomas, there are also reports of either a decrease or no change in expression compared to normal tissue." (PMID 32335811, 2020). "In non-functioning adenomas as well as in PRL-secreting adenomas the expression of Bcl-2 found decreased and BAX protein was increased when associated with pituitary tumor progression." (PMID 29104246, 2017). "In a separate experiment we studied the rate at which adenomas developed in the presence or absence of functional Bcl-2." (PMID 26956214, 2016). "There has been only one study of bcl-2 in FAP patients, but only adenomas were analysed." (PMID 23476634, 2013).
adenoma (continued). "The most extensive study indicated that Bcl-2 is overexpressed in normal adrenal cortex, without distinct staining difference between normal and pathological tissue (hyperplasia, adenomas and carcinomas)." (PMID 12085205, 2002). "Indeed recent studies show that BCL-2 is downregulated upon APC mutation and inhibition of Bcl-XL was shown to impair adenoma outgrowth, although BCL-XL inhibition was not effective on preexisting adenomas." (PMID 36860494, 2022). "Whether Bcl-2 positivity found in some carcinomas and non-functioning adenomas may constitute, in the latter, a negative prognostic marker is still unknown." (PMID 12085205, 2002). "miR-21 was found to be significantly (p < 0.01) upregulated in adenoma and tumour samples compared to the healthy colonic tissue controls and could explain the altered expression of genes for which DNA methylation changes do not appear to play role (e.g. BCL2, MAL, PTGS2)." (PMID 26482433, 2015). "This is the first study to show caspase-3 expression along the adenoma-carcinoma sequence in FAP patients and to show that caspase-3 expression occurs early in the sequence, but persists into invasive carcinomas, unlike the expression of the antiapoptotic protein bcl-2." (PMID 23476634, 2013).
autoimmune disease (28 papers, 2014 to 2025). A disorder resulting from loss of function or tissue destruction of an organ or multiple organs, arising from humoral or cellular immune responses of the individual to their own tissue constituents. "As an important factor regulating apoptosis, BCL2 has been associated with the development and progression of cancer and autoimmune diseases, and several drugs targeting BCL2 have been developed." (PMID 35677450, 2022). "The abnormalities of Bcl-2 function have been implicated in many diseases including cancer, neurodegenerative disorders and autoimmune diseases." (PMID 26879955, 2016). "Given their central role at regulating immune cell survival, BCL2 proteins may also be implicated in autoimmune diseases characterized by insufficient apoptosis of autoreactive immune cells." (PMID 40113751, 2025). "It was shown that an increased IL-10 level is associated with an elevated production of autoantibody in patients with autoimmune diseases via altering the regulation of B-cell bcl-2 expression." (PMID 39064007, 2024). "After in vitro stimulation with CpG for 6 days, plasmablasts were more viable after treatment with Bcl-2 inhibitors for 24 h compared to naïve or memory B cells of healthy controls and autoimmune diseases." (PMID 37993903, 2023). "The abnormalities of BCL2 participate in the pathogenesis of numerous human diseases, including malignancies, neurodegenerative diseases, and autoimmune diseases." (PMID 34784951, 2021). "Less is known about the contribution of STAT3-induced cell survival for autoimmune diseases and whether Bcl2 and inhibitor of apoptosis (IAP) family members play a role, as has been documented for cancer cells." (PMID 33557010, 2021). "Given that BBR has been shown to regulate Treg cells by modifying the microbiota in a chemically induced IBD model and to regulate Bcl-2 in an in vitro autoimmune disease model, we next examined the change in the frequency of Foxp3+ Treg cells and the Bcl-2 expression." (PMID 31417110, 2019). "Additionally, other genes that were identified in our study, including BCL2, OAS1, MX1, and SKP2 have been previously associated with various autoimmune diseases." (PMID 29387060, 2017). "It is well known that Bcl2 is also involved in cancer and autoimmune diseases." (PMID 26980943, 2016). "Thereby, enhanced expression levels of BCL2 contribute to development of autoimmune diseases." (PMID 26919255, 2016). "The results indicate that the compounds MJ19 and MJ20 have the greatest effect on the induction of pro-inflammatory (IL6, IL8) and antiapoptotic (BCL2, MDM2) genes, suggesting their potential use in therapies for inflammatory and autoimmune diseases." (PMID 40725171, 2025). "Expression of survival markers CD127 and BCL-2 by MAIT cells was decreased in women with long-term type 1 diabetes and another autoimmune disease compared with other groups." (PMID 34350463, 2021). "As in other autoimmune diseases, MSCs from patients with SLE exhibited increased frequencies of apoptosis, as evidenced by the downregulation of Bcl-2 and upregulation of Bax, and higher intracellular ROS levels than those in normal MSCs." (PMID 34521481, 2021). "It has been shown that the alteration of the balance between the expression of BCl-2 and FAS-L/FAS-R is involved in the pathology of various pathologies, such as autoimmune diseases, HIV, neurodegenerative disorders, cancer." (PMID 34178720, 2021). "Even in models of relatively rare autoimmune diseases like primary sclerosing cholangitis, inhibition of the SASP of senescent cholangiocytes through Bcl-2 inhibition reduced tissue damage and subsequent fibrosis." (PMID 32185730, 2020).
autoimmune disease (continued). "In women with long-term type 1 diabetes and an associated autoimmune disease, there was an increase in CD69 expression and a decrease in the survival B-cell lymphoma 2 (BCL-2) (p < 0.05) and CD127 (IL-7R) (p < 0.01) marker expression compared with women without a concomitant autoimmune disorder." (PMID 34350463, 2021).